GPX4 (glutathione peroxidase 4)
Diseases named in the same sentence as GPX4 in open-access papers (continued):
Sharing a sentence is not in itself a finding about the gene and the disease.
breast carcinoma (continued). "Additionally, in the context of these specific genes, GPX4 has been found to modulate the apoptosis of breast cancer cells by regulating mitochondria-mediated apoptosis, thereby influencing their resistance to drugs." (PMID 38312660, 2024). "This hypothesis was confirmed in our study, which revealed a significant decrease in the levels of phosphorylated EGFR, PI3K, AKT, and GPX4 in ORes-treated breast cancer cells." (PMID 39881871, 2024). "Based on these findings, we hypothesised that ORes exert their effects by inhibiting EGFR, thereby modulating the PI3K-AKT pathway, suppressing GPX4 activity, and inducing ferroptosis in breast cancer cells." (PMID 39881871, 2024). "In addition, recent studies have shown that the GPX4 inhibitor RSL3 can enhance chemosensitivity in luminal breast cancer by synergizing with other chemotherapeutic agents through ferroptosis." (PMID 39759144, 2024). "Similarly, albiziabioside A induces the apoptosis and ferroptosis of breast cancer cells, accompanied by the downregulation of the ferroptosis-inhibiting GPX4 gene." (PMID 38892270, 2024). "Additionally, immunohistochemistry (IHC) was used to evaluate GPX4 expression in breast cancer tissues." (PMID 39881871, 2024). "GPX4 inhibitors induced ferroptosis and blunted breast cancer progression." (PMID 38906931, 2024). "Additionally, the small molecule DMOCPTL, derived from a natural parthenolide, binds directly to GPX4, inducing its ubiquitination and leading to ferroptosis in breast cancer cells." (PMID 39857625, 2024). "Notably, EGFR knockdown in MDA-MB-231 cells reduced GPX4 expression, indicating that EGFR inhibition lowers GPX4 levels in breast cancer cells." (PMID 39881871, 2024). "In addition to ferroptosis, gallic acid also triggers the apoptosis of breast cancer cells by downregulating the ferroptosis-inhibiting GPX4 gene." (PMID 38892270, 2024). "extracted an active compound, glycyrrhetinic acid, from the traditional herb licorice, and found that it could reduce the activity of GSH and GPX4, exacerbate lipid peroxidation, and induce ferroptosis in breast cancer cells." (PMID 39664391, 2024). "Further inhibition of FGFR4 in drug-resistant cells revealed that the expression of SLC7A11 and GPX4 was significantly reduced, which promoted ferroptosis to inhibit tumorigenesis, thus restoring the sensitivity of drug-resistant breast cancer cells to anti-HER2." (PMID 38550378, 2024). "A burgeoning body of evidence suggests that ferroptosis can be induced in tumor cells through inhibition of System Xc-, depletion of glutathione (GSH), and inactivation of glutathione peroxidase 4 (GPX4), thereby counteracting the mechanisms of drug resistance in breast cancer." (PMID 39759144, 2024). "Furthermore, METTL16 enhanced GPX4 expression in a m6A-dependent manner, thus promoting the malignant progression of breast cancer via inhibiting ferroptosis." (PMID 38065948, 2023). "Additionally, researches have demonstrated that GPX4 dependence makes drug-resistant breast cancer cells vulnerable to ferroptosis brought on by GPX4 inhibition." (PMID 37833746, 2023). "High expression of GPx4 was detected in breast cancer 6, liver cancer 7, lung cancer 8 and glioma 9, suggesting that GPx4 may play a role as an oncogenic gene." (PMID 36923926, 2023). "Moreover, high RUNX1-IT1 was linked to poor prognosis, and a strong positive correlation between RUNX1-IT1 and GPX4 was observed in clinical breast cancer tissues." (PMID 37036576, 2023). "Moreover, compounds 78 (5 μM), 76 (10 μM), and more effectively the conjugate 77 (2 μM) elevated MDA levels and decreased GPX4 expression in human HCT116 CRCs282 or in human MCF‐7 breast cancer cells." (PMID 36658724, 2023). "Next, we tested whether the expression of GPX4 gene can also decrease simultaneously with the expression of IGFBP6 gene in breast cancer tissue." (PMID 36714261, 2023).
breast carcinoma (continued). "To test whether RL2 treatment induced ferroptosis in the breast cancer cell lines tested, we monitored changes in one of the ferroptosis markers, GPX4." (PMID 38132099, 2023). "In addition, GPX4 was significantly overexpressed in breast cancer tissues in comparison to normal tissues, and its expression was strongly positively correlated with RUNX1-IT1 expression." (PMID 37036576, 2023). "NUAK2 is amplified along with MDM4 in a subset of breast cancers, particularly the claudin-low subset, suggesting that this may predict vulnerability to GPX4 inhibitors." (PMID 35523770, 2022). "Erastin also suppresses the expression of GPX4 in breast cancer, especially in TNBC." (PMID 36467032, 2022). "Nrf2 can promote drug resistance of breast cancer cells by regulating System Xc−/GSH/GPX4 axis." (PMID 36105219, 2022). "The close proximity of NUAK2, which we find is commonly co-amplified with MDM4 in breast cancer, may fortuitously confer a vulnerability to GPX4 inhibition that could be exploited for therapy." (PMID 35523770, 2022). "In the case of breast cancer, xCT determines the expression of GPX4, which is strongly upregulated compared to that in normal cells, so that breast cancer cells could become resistant to oxidative-stress-inducing drugs." (PMID 36009223, 2022). "Moreover, it has been reported that Ketamine inhibits proliferation and promotes ferroptosis of by targeting KAT5/GPX4 signaling in breast cancer cells." (PMID 35685642, 2022). "GPX4 expression in breast cancer was still little investigated." (PMID 33472669, 2021). "‘Addiction’ of breast cancer cells to xCT/GPX4 anti-ferroptotic machinery." (PMID 33672555, 2021). "Furthermore, apoptosis, hypoxia, invasion, cell cycle and DNA damage were significantly related to GPX4 expression in breast cancer cells." (PMID 33472669, 2021). "GPX4 expression distribution with t-SNE showed that breast cancer cells with high GPX4 expression tended to cluster together in two patients, which suggests that GPX4 may promote the malignant progression of breast cancer." (PMID 33472669, 2021). "Well-established chemical inducers of ferroptosis, such as the GPX4 inhibitor Rsl-3 and the xCT inhibitor Erastin, and their derivatives, are currently being explored as potential therapeutics for breast cancer therapy and have been shown to exert toxicity in these and other cancer cells." (PMID 33672555, 2021). "A recent study showed a strong negative correlation between breast tumor grade progression and GPx4 expression in breast cancer tissues, and its downregulation may be related to the poor prognosis of patients with invasive ductal carcinoma of the breast." (PMID 32571353, 2020). "The degree of GPX4 downregulation was similar between the two cell lines, but the degree of ferroptosis in the two cells was different, indicating that GPX4 is not the most important regulator in the process of curcumin-induced breast cancer cell ferroptosis." (PMID 33294119, 2020). "Interestingly, drug-tolerant persister breast cancer cells acquire a dependency on GPX4, which means they are vulnerable to ferroptosis induced by GPX4 inhibition." (PMID 33292585, 2020). "In contrast, a previous study showed a negative relationship between polymorphisms in GPX4 and susceptibility to breast cancer." (PMID 33292585, 2020). "Interestingly, GPx4 expression was down-regulated in breast cancer cells compared with normal breast cells." (PMID 32571353, 2020). "Furthermore, miR-324-3p can increase the production of lipid reactive oxygen species (ROS) by targeting glutathione peroxidase 4 (GPX4) in breast cancer cells, resulting in ferroptosis while preventing tumor cells from spreading distant, which offers a new potential target for the treatment of TNBC." (PMID 41614928, 2026).
breast carcinoma (continued). "Interestingly, while each of the lung, melanoma and breast cancer persister cell types we analyzed here are deficient in one or more anti-ferroptotic factors including NRF2, GSH or in anti-ferroptotic enzymes GPX4, DHODH or VKORC1L1, all were deficient in FSP1." (PMID 40909720, 2025). "A study on the mechanism by which metformin-induced ferroptosis inhibits the proliferation of breast cancer cells found that metformin can increase intracellular Fe2+ and lipid ROS levels, and can also induce ferroptosis in breast cancer cells by up-regulating miR-324-3p to inhibit GPX4 expression." (PMID 39944825, 2025). "GPX4 acts as a central inhibitor of ferroptosis in cancer cells, which enhances the cytotoxicity of chemotherapeutic agents in breast cancer as well as the sensitivity to radiotherapy, and thus GPX4 expression level is negatively correlated with the prognosis of breast cancer patients." (PMID 40949160, 2025). "Therefore, we propose that THSG may prevent the breast cancer growth by decreasing xCT and GPX4 expression and arresting breast cancer cells in the G2/M phase." (PMID 39944401, 2024). "Thus, metformin targets the miR‐324‐3p/GPX4 axis to induce ferroptosis in breast cancer." (PMID 38140764, 2024). "Notably, drug-resistant breast cancer cells often exhibit dependence on GPX4, suggesting that its inhibition could potentially overcome chemoresistance." (PMID 39759144, 2024). "Since GPX4 is one of the main defense mechanisms against lipid peroxidation and is the principal regulator of ferroptosis, authors believe that metformin induces ferroptosis in breast cancer cells through the regulation of the miR-324-3p—GPX4 signaling pathway." (PMID 39796103, 2024). "Additionally, our prognostic analysis of genes encoding proteins in the EGFR/PI3K/AKT signalling pathway and GPX4 in breast cancer revealed that reduced activation of the EGFR/PI3K/AKT pathway and decreased GPX4 expression were associated with better patient outcomes." (PMID 39881871, 2024). "Therefore, GPX4 can be a potential target to overcome drug resistance in breast cancer." (PMID 37760042, 2023). "Taken together, our data reveal that RUNX1-IT1 promotes breast cancer carcinogenesis through blocking ferroptosis via elevating GPX4, targeting of the previously unappreciated regulatory axis of RUNX1-IT1/IGF2BP1/GPX4 may be a promising treatment for patient with breast cancer." (PMID 37036576, 2023). "Accordingly, we speculated that GPX4 knockdown might induce apoptosis of breast cancer cells." (PMID 33472669, 2021). "The role of xCT in driving both glutathione production and the expression of glutathione-utilizing enzymes such as GPX4 suggests that its expression may promote survival under oxidative stress conditions for breast cancer cells that have elevation in xCT expression." (PMID 33672555, 2021). "Although we hypothesized that DOBS would modify associations with selenoprotein genes, only one SNP in GPX4, SELS, and TXNRD1 that interacted with DOBS remained statistically significantly associated with breast cancer after adjustment for multiple comparisons." (PMID 24278290, 2013). "In breast cancer, the up-regulation of METTL16 expression leads to increased m6A modification of GPX4 mRNA, enhancing the expression of GPX4." (PMID 41459114, 2026). "Six ferroptosis-related genes (SLC7A11, GPX4, FTH1, NQO1, NFE2L2, SQSTM1) demonstrated consistent upregulation across all breast cancer subtypes, with higher expression observed in more aggressive tumors." (PMID 42074090, 2026). "In breast cancer, METTL16 can stabilize the expression of GPX4 by increasing its m6A methylation, and GPX4 further reduces the levels of intracellular iron, Fe2+ and lipid reactive oxygen species (ROS), inhibits the occurrence of ferroptosis." (PMID 41522342, 2026).
breast carcinoma (continued). "GPX4-AUTAC, exploiting TRAF6-mediated ubiquitination and p62-driven autophagy, selectively degrades GPX4, inducing ferroptosis in breast cancer, especially in combination with chemotherapy." (PMID 40919170, 2025). "In breast cancer, simvastatin inhibits HMGCR expression and suppresses the mevalonate (MVA) pathway and glutathione peroxidase 4 (GPX4) production, which induces cancer cell ferroptosis." (PMID 40140647, 2025). "S-palmitoylation of PHGDH and FASN promotes chemoresistance in breast cancer, while palmitoylation of ACACA and GPX4 influences lipid metabolic reprogramming and ferroptosis resistance, respectively." (PMID 40626019, 2025). "In breast cancer, METTL16 epigenetically upregulates GPX4 through m6A modification, thereby inhibiting ferroptosis and promoting cancer progression." (PMID 39248438, 2024). "miR-324-3p and miR-382-5p induce ferroptosis by targeting GPX4 and SLC7A11’s 3’-UTR, inhibiting breast cancer progression." (PMID 39664391, 2024). "For alloimperatorin, it induces the antiproliferation, apoptosis, and ferroptosis of breast cancer cells by downregulating the ferroptosis-inhibiting genes (SLC7A11, GPX4, and phosphorylated AIFM1)." (PMID 38892270, 2024). "Similar to circRNAs in the liver metastasis of breast cancer, these findings demonstrate that circ0060467 regulates AIFM2 and GPX4 expression by sponging miR-6805 via a ceRNA mechanism." (PMID 38244593, 2024). "GPX4 and ferroportin have been shown significantly lower expression in TNBC sections compared to other breast cancers, providing a therapeutic environment for ferroptosis." (PMID 37179385, 2023). "Multiple ferroptosis-associated regulators, such as glutathione (GSH), glutathione peroxidase 4 (GPX4), NFE2L2, superoxide dismutase (SOD), lipoxygenase, and coenzyme Q, are capable of remodeling breast cancer progression." (PMID 37928550, 2023). "Together, these observations predict that claudin-low breast cancers will generally exhibit higher NUAK2 expression and enhanced vulnerability to GPX4 inhibition." (PMID 35523770, 2022). "Cluster #0 is the largest cluster with 16 keywords: gastric cancer, cisplatin resistance, targeting ferroptosis, GPX4, neck cancer, RSL3, NRF2, breast cancer cell, protective effect, inhibiting ferroptosis, and so on." (PMID 35087622, 2022). "In breast cancer, TFAP2C has multiple functions in regulating the expression of GPX4 in response to selenium supplementation." (PMID 35402284, 2022). "The results showed the expression and distribution of GPX4, GSDMD, GSDMC, IL18 in breast cancer and normal tissues." (PMID 36138348, 2022). "GPX4, as GPX1, was found to be highly expressed in different cancer tissues, including breast cancer, and also correlated with shorter patient survival." (PMID 35158912, 2022). "Metformin enhanced ferroptosis in breast cancer cells by altering the stability of SLC7A11, downregulating GPX4 activity and inhibiting the autophagy induced by H19." (PMID 36505465, 2022). "Erastin depletes GPX4 and GPX1 levels in breast cancer cells by inhibiting xCT-dependent extracellular reduction." (PMID 36009223, 2022). "Some reports showed that genetic variations in some selenoproteins, such as GPX1, GPX3, GPX4, SELENOS, and TXNRD1, are correlated to breast cancer development." (PMID 35158912, 2022). "It showed a low mRNA expression trend of GPX4, GSDMD and GSDMC in all three types of breast cancer cells, while the mRNA expression of IL18 varied." (PMID 36138348, 2022). "A previous study showed that some ferroptosis-related genes had the potential to be promising treatment targets in breast cancer, such as iron, ACSL4, GPX4, SLC7A11 and SLC3A." (PMID 33672990, 2021). "MCF (human breast cancer cell line) cells, which have a higher level of GPx4, were more resistant to PDT than MDA-MB-231 (triple-negative human breast cancer cell line) cells, which have a lower level of GPx4." (PMID 34439326, 2021).
breast carcinoma (continued). "Some breast cancer cells acquire the ability of drug resistance through GPX4, namely those which are vulnerable to ferroptosis induced by GPX4 inhibition, suggesting that the GPX4 inhibitor might become a potential agent to overcome drug resistance in breast cancer." (PMID 33672990, 2021). "Erastin depletes levels of the antioxidant selenoproteins GPX4 and GPX1 in breast cancer cells by inhibiting xCT-dependent extracellular reduction which is required for selenium uptake and selenocysteine biosynthesis." (PMID 33672555, 2021). "LncRNA LIPE-AS1 was co-expressed with 5 ferroptosis-related genes (HRAS, PHKG2, MAPK14, EGLN2, and GPX4), including 4 ferroptosis driver and 1 ferroptosis suppressor, and we found that LIPE-AS1 was a protective factor for breast cancer patients’ prognosis." (PMID 34164433, 2021). "Four GPXs family genes had the significant ability to distinguish breast cancer tissues from normal breast tissues, including GPX2, GPX3, GPX4 and GPX8." (PMID 32782436, 2020). "To confirm the effect on GPx4 activity by ML162, we also measured GPx4 activity in multiple endometrial and breast cancer cell lines after treatment with ML162." (PMID 31527591, 2019). "They evaluated the levels of GPX4 protein expression in breast cancer cells and discovered that TNBC cells showed higher GPX4 expression than non-TNBC cells, with GPX4 deficiency inducing ferroptosis." (PMID 40969276, 2025). "Pyruvate carboxylase (PC) is an anaplerotic enzyme essential for oxidative stress protection, although its relationship with GPX4 in obesity-related breast cancer is not established." (PMID 40001204, 2025). "In summary, METTL16 promotes breast cancer progression by regulating FBXO5-mediated proliferation and EMT as well as GPX4-mediated ferroptosis resistance, and targeting METTL16 via advanced nanoparticle-based delivery represents a promising therapeutic strategy for TNBC." (PMID 41322419, 2025). "Notably, TetC‐induced ferritin cell death demonstrated inhibition of GPX4 expression and activation of NCOA4‐mediated ferritin phagocytosis in breast cancer cells." (PMID 38140764, 2024). "The results revealed that breast cancer tissues exhibited lower expression levels of SAT1, ALOX5, ALOX12, ATF3, ATF4, GPX4 and NFE2L2 compared to normal tissues; conversely, higher expression levels of ALOX15, ALOXE3 and HO‐1 were observed in breast cancer tissues than in normal tissues." (PMID 38516826, 2024). "Growing evidence indicates that inducing ferroptosis through various mechanisms, particularly by inhibiting System Xc-, depleting glutathione (GSH), and inactivating glutathione peroxidase 4 (GPX4), holds great potential in overcoming drug resistance in breast cancer." (PMID 39759144, 2024). "Additionally, glycyrrhetinic acid induces ferroptosis by promoting ROS and reducing GPX4 and GSH activity in breast cancer cells." (PMID 39664391, 2024). "Other studies of other cancer types have also reported similar results to those of the current study, such as a higher survival rate in patients without distant metastasis in breast cancer with high GPX4 expression." (PMID 39594843, 2024). "Therefore, our study suggests that RUNX1-IT1 is a novel oncogenic lncRNA in breast cancer, dysregulation of RUNX1-IT1/IGF2BP1/GPX4 is responsible for breast cancer carcinogenesis and progression." (PMID 37036576, 2023). "COH-BR1 breast cancer cells co-cultured with 7α-cholesterol hydroperoxide showed that GPX4 reduced lipid peroxide in a glutathione-dependent manner, and treatment with RSL3 inactivated GPX4 and suppressed its peroxide reduction." (PMID 37046995, 2023). "In samples obtained from breast cancer patients, METTL16 is overexpressed, which increases the rate of m6A modification on GPX4 mRNAs, increasing their stability and resulting in upregulation of GPX4." (PMID 37497000, 2023).